KIT (KIT proto-oncogene, receptor tyrosine kinase)
Diseases named in the same sentence as KIT in open-access papers (continued):
Sharing a sentence is not in itself a finding about the gene and the disease.
mastocytosis (continued). "In turn, only 5/34 (15%) adult mastocytosis patients who were not screened for the KIT mutation have been reported so far to respond to imatinib." (PMID 28978170, 2017). "This might explain at least in part why treatment with KIT inhibitors alone so far has been disappointing in most published clinical trials for mastocytosis." (PMID 29088753, 2017). "Furthermore, only 29% of transgenic mice expressing human KIT D816V developed mastocytosis at an old age (> 12 months)." (PMID 29088753, 2017). "Mutations in the tumor suppressor gene TET2 act in synergy with KIT D816V mutation, enhance its oncogenic potency, and induce aggressiveness of the mastocytosis, but in contrast to other mutations have not been associated with decreased overall survival." (PMID 28775983, 2017). "The cause of mastocytosis is not known but activating mutations in the proto-oncogene receptor tyrosine kinase, KIT, are found in most patients with mastocytosis." (PMID 27196054, 2016). "Mutations of KIT are the dominant genetic lesion in GIST and mastocytosis." (PMID 27777718, 2016). "There are some hotspots of somatic mutations of KIT and the hotspots in GIST and mastocytosis are different with the reason unknown." (PMID 27777718, 2016). "The different phenotypes mediated by various germline mutations of KIT might reflect the cellular context dependent transforming ability of kit mutations and explain the difference in hotspots of KIT mutations between GIST and mastocytosis." (PMID 27777718, 2016). "The mechanism behind that might reflect the tissue-specific activation mechanism of KIT mutations and further explain the difference in hotspots of KIT mutations between GIST and mastocytosis." (PMID 27777718, 2016). "In the KIT WT subgroup, 2 patients (33%) had a history of pediatric mastocytosis, whereas none of the 3 patients in the group with positive KIT D816V mutation had a pediatric mastocytosis history." (PMID 27602777, 2016). "Unlike mastocytosis in which exon 17 mutation D816V is the dominant KIT mutation, exon 11 mutation in KIT is most common in GIST, and exon 9 and 13 mutations are also often seen in GIST but to a less extent." (PMID 27777718, 2016). "The reason for the difference in hotspots of KIT mutations between mastocytosis and GIST remains unknown, the study of KIT mutations in different host cells might give some clues." (PMID 27777718, 2016). "Systemic mastocytosis was repeatedly excluded by morphology and by the absence of the KIT D816V mutation, and serum tryptase levels were normal." (PMID 25894969, 2015). "Overall 75% of pediatric patients have some alternations in KIT, laying support to the now prevailing hypothesis that childhood mastocytosis is a clonal disease, although the spectrum of the disease and mutations are narrower than those seen in adults." (PMID 26158763, 2015). "Although KIT D816V mutations are present in all subtypes of mastocytosis, the presence of the KIT mutation does not always correlate with a specific sub-type of SM or its prognosis." (PMID 26158763, 2015). "Overall, these clinical findings suggest that the presence of ASXL1 mutations, besides KIT and TET2 may also contribute to the prognosis and survival of mastocytosis patients." (PMID 26158763, 2015). "Detection of the KIT mutation in the dermis is indicative of mastocytosis in the skin, but it is not diagnostically indicative of systemic involvement." (PMID 24141298, 2013). "Importantly, RIN3 over-expression sensitized a mastocytosis cell line to treatment with the KIT inhibitor imatinib." (PMID 23185384, 2012). "In this context, it will be interesting to assess whether miR-221/-222 could be part of a molecular mechanism involved in KIT regulation specifically in mastocytosis." (PMID 22022537, 2011).
mastocytosis (continued). "Unlike the wild-type KIT whose activation needs ligand binding, the gain-of-function mutations of KIT that occur in GISTs and other malignancies such as mastocytosis confer the ligand-independent activation to the receptor, leading to uncontrolled signaling and eventually cell transformation." (PMID 38951864, 2024). "Neither study reported KIT M541L as significantly associated with the mastocytosis." (PMID 39037378, 2024). "Other variants in this gene have been documented in association with isolated mastocytosis and piebaldism (OMIM# 172800), suggesting that KIT variants inducing either GIST or mastocytosis may activate different downstream signaling pathways resulting in dysregulation of mast cells and/or ICC8,9." (PMID 38538628, 2024). "In patients with mastocytosis, in some instances, KIT M541L may be disease-modifying." (PMID 39037378, 2024). "Moreover, no evident correlation between KIT mutations and clinical phenotype and the prognosis of pediatric mastocytosis was found." (PMID 38066824, 2023). "Furthermore, the clinical course of mastocytosis is affected by the presence of KIT mutations in non-mast cell lineages; the more mast cell lineage-restricted progenitors are affected, the more indolent the disease." (PMID 35884535, 2022). "In recent years, the application of sensitive, allele-specific quantitative polymerase chain reaction (ASqPCR) KIT D816V mutation analysis in PB has become a standard screening examination in adults with manifestations of CM and those with suspected mastocytosis without cutaneous signs and symptoms." (PMID 33806685, 2021). "By contrast, patients with childhood onset mastocytosis may not have detectable KIT mutations or may express KIT mutations other than D816V (in exons 8, 9, 11 or 17)." (PMID 33407701, 2021). "Due to the rarity of these SM cases lacking exon 17 KIT mutations (≤ 4%), a critical review of mastocytosis cases treated with imatinib who have been reported in the literature is also provided to better estimate the response rates to imatinib according to the KIT mutational status." (PMID 28978170, 2017). "Overall, 46 patients with mastocytosis lacking the D816V KIT mutation and other extracellular membrane/transmembrane KIT mutations who were treated with imatinib and further evaluated for response to therapy have been reported, with an overall response rate of 80% (37/46 cases)." (PMID 28978170, 2017). "Although KIT inhibitors showed very good inhibitory effects on mast cells in vitro, however, treatment with KIT inhibitors alone so far has been disappointing in most published clinical trials for mastocytosis, probably due to development of resistance to kinase inhibitors." (PMID 29088753, 2017). "In the case of mastocytosis, the D816V mutation in the catalytic domain of KIT is considered a major predisposing factor in the progression of disease, and approaches to downregulate KIT activation could be considered a reasonable strategy for the treatment of mastocytosis." (PMID 28332308, 2017). "Because mast cells bearing mutations in KIT from patients with mastocytosis could not be obtained in sufficient numbers, we used mast cell lines with KIT mutations derived from a patient with mast cell leukemia, namely HMC-1.1 and HMC-1.2." (PMID 27611333, 2016). "Furthermore, the D816V KIT mutation present in the majority of patients with mastocytosis is not adequate to induce aggressive MC disorders in isolation." (PMID 22438059, 2012). "For example, mastocytosis, urticaria pigmentosa, and diffuse hyperplasia of ICC with progression to distinct GISTs have been associated with mutations involving the JM domain of KIT, while mutations that affect the kinase domain essentially lack mastocytosis and urticaria pigmentosa." (PMID 21559207, 2011).
mastocytosis (continued). "Furthermore, mutations in exon 17 of the c-KIT proto-oncogene, where mutations are most commonly seen in human patients with mastocytosis, do not contribute to the aberrant localization of KIT in canine cutaneous MCTs." (PMID 16579858, 2006). "The high degree of conservation between the human and the dog suggests that a change in a single amino acid of the kinase domain could alter the function of the KIT protein, potentially producing a constitutively activated protein, as is seen in human mastocytosis patients." (PMID 16579858, 2006). "However, unlike human mastocytosis patients, kinase domain c-KIT mutations do not appear to play a role in the progression of canine MCTs." (PMID 16579858, 2006). "The targeting of KIT and the JAK-STAT pathway have proven effective in the treatment of systemic mastocytosis and PMF with KIT inhibitors and JAK inhibitors, respectively, but are outside the scope of this review." (PMID 39997326, 2025). "MITF impairment reduces KIT expression in both GIST and HMC-1 cells—a cellular model of mastocytosis." (PMID 41168571, 2025). "In 2006, the FDA approved imatinib for adult patients with aggressive SM (ASM) without the D816V KIT mutation or with unknown or unavailable KIT mutational based on clinical data from single case reports and a small series of patients with mastocytosis treated with this drug." (PMID 39649724, 2024). "US8461179B1 uncovers dihydronaphthyridine derivatives that inhibit c-KIT and that have utility to treat GIST, mast cell leukemia, or mastocytosis." (PMID 34451807, 2021). "The transfection with KIT D816V converted ROSAKIT WT cells into an SCF-independent clone, ROSAKIT D816V, which produced a mastocytosis-like disease in mice." (PMID 33687603, 2021). "Although KIT mutations, particularly KIT D816V, have been considered to serve as key mutations in mastocytosis, an increasing body of data has indicated that other events (e.g., tropomyosin-related kinase [TRK]) may play important roles in the pathogenesis of mastocytosis." (PMID 34063170, 2021). "Besides inhibition of BCR-ABL, nilotinib has also shown in vitro activity against other kinases, particularly PDGFRα and KIT, which has led to the investigation of its potential clinical utility in diseases driven by these kinases such as gastrointestinal stromal tumors (GISTs) and mastocytosis." (PMID 32346366, 2020). "This review highlights the central roles of SFKs in AML and mastocytosis, and their interconnection with FLT3 and KIT oncoproteins." (PMID 32708273, 2020). "Since the KIT/D816V mutation has been reported in several hematological malignancies, including mastocytosis and core binding factor acute myeloid leukemia (CBF AML), this suggests that the interaction found is relevant for KIT function." (PMID 29910466, 2018). "Therefore, a compound that alters neoplastic mast cell proliferation by targeting C-KIT expression or downstream KIT signalling, offers insight into new therapeutic approaches for mastocytosis." (PMID 36970068, 2023). "In some adult patients with mastocytosis, the tests required for a full diagnosis and WHO classification - especially bone marrow analysis including flow cytometry and KIT mutation analysis - were not always performed." (PMID 33391475, 2021). "In mastocytosis, many of these regulatory systems have been shown to no longer control KIT signaling." (PMID 33401724, 2021). "Mutations in the kinase domain, frequently observed in the A-loop in cases of mastocytosis, AML and human germ cell tumors, are believed to strongly influence the A-loop conformation, contributing in the displacement of KIT equilibrium towards the active conformation." (PMID 25079768, 2014). "Hence, by facilitating KIT down regulation, RIN3 sensitizes mastocytosis cells to the therapeutic kinase inhibitor imatinib." (PMID 23185384, 2012).
mastocytosis (continued). "However, we are increasingly seeing patients without cutaneous mastocytosis and with only 1–2 minor WHO criteria in the bone marrow (including KIT mutation and/or aberrant expression of CD2/CD25)." (PMID 39877259, 2025). "Although development of a KIT mutation is not directly related to the increased number of copies of the TPSAB1 gene, the high prevalence of HαT in mastocytosis hints at a potential pathogenic role of germline α-tryptase-encoding TPSAB1 copy number gains in disease development." (PMID 40649802, 2025). "This suggests that patients who do not express KIT, such as the patient in this case, may experience less mastocytosis and have a better prognosis." (PMID 40950415, 2025). "KIT-negative mastocytosis, as in our case, may require a tailored approach, but the primary goal remains preventing severe reactions and improving quality of life." (PMID 40557010, 2025). "However, a normal tryptase level does not exclude a MC disorder and therefore, in the suspect of mastocytosis, blood KIT testing and BM biopsy are considered essential." (PMID 34282774, 2021). "Interestingly, some patients with mastocytosis have no molecular alterations within KIT, which suggests that they have alterations in genes other than KIT that affect the clinical presentation of the disease." (PMID 33806685, 2021). "Some human mastocytosis (six of 15 cutaneous mastocytosis cases) expressed KIR2DL4 protein, however, whether KIR2DL4 stimulation suppresses the growth of KIT-mutated neoplastic mast cells in vitro has not been determined." (PMID 32023940, 2020). "Some germline mutations of KIT, such as Y553C, W557R, D579del and K642E, only induce GIST but not mastocytosis, the study of these KIT mutants might elucidate the specific transformation mechanism of KIT mutations in ICC." (PMID 27777718, 2016). "Although new generations of KIT‐targeting kinase inhibitors may pave the way for MC‐directed approaches in advanced mastocytosis, no curative therapy has yet emerged for any category of mastocytosis." (PMID 35876458, 2022). "Therefore, comparative studies of MCs disorders may represent an opportunity to improve our knowledge on both mastocytosis and c-KIT driven tumors for diagnosis in case of c-KIT wild type state and/or with the aim to develop novel treatment options that can be translated in human patients." (PMID 26562302, 2015). "Data from single case reports and small series of mastocytosis patients treated with imatinib prompted the U.S. Food and Drug Administration (FDA) to approve in 2006 its use in adults with ASM lacking the D816V KIT mutation or with unknown KIT mutational status." (PMID 28978170, 2017).
acute myeloid leukemia (180 papers, 2004 to 2026). Acute myeloid leukemia (AML) is a group of neoplasms arising from precursor cells committed to the myeloid cell-line differentiation. "This case is reported due to its novelty in demonstrating the efficacy of avapritinib, a selective KIT inhibitor, in a rare systemic mastocytosis-associated acute myeloid leukemia (SM-AML) patient with non-D816V KIT mutations and RUNX1::RUNX1T1 fusion." (PMID 41473436, 2025). "Mutated receptor tyrosine kinases (MT-RTKs) such as internal tandem duplication of FMS-like tyrosine kinase 3 (FLT3 ITD) and a point mutation KIT D816V are driver mutations for acute myeloid leukemia (AML)." (PMID 32811837, 2020). "KIT D816 mutations (KIT D816mut) are strongly associated with systemic mastocytosis (SM) but are also detectable in acute myeloid leukemia (AML), where they represent an adverse prognostic factor in combination with core binding factor (CBF) fusion genes." (PMID 30635631, 2019). "Gain-of-function mutations in KIT, a member of the receptor type tyrosine kinases, are observed in certain neoplasms, including mast cell tumors (MCTs) and acute myelogenous leukemias (AMLs)." (PMID 24713856, 2013). "Point mutations localized in the JMR or the PTK of KIT were identified in various forms of cancer (gastro-intestinal stromal tumors GISTs, acute myeloid leukemia AML, mast cell leukemia MCL, germ cell tumors...) and mastocytosis." (PMID 22927810, 2012). "Aside from SM, acute myeloid leukemia (AML) was the most common MNs with KIT mutation, which was detected in 4%−6% de novo AML, most frequently occurred in core binding factor AML (CBF AML)." (PMID 41557053, 2026). "Following a comprehensive bone marrow assessment, the patient was diagnosed with AML1::ETO positive acute myeloid leukemia (AML) harboring a KIT mutation." (PMID 39839634, 2024). "KIT is a proto-oncogene that can cause AML, most often core-binding factor acute myeloid leukemia (CBF-AML), and gastrointestinal stromal tumors." (PMID 37513844, 2023). "Acute myeloid leukemia, seminoma/dysgerminoma and sinonasal NK/T-cell lymphoma, neoplasms related to KIT mutations (often in exon 17), at the best of my knowledge have never been described in germline KIT-mutants (curiously, some familial germ-cell tumors revealed somatic KIT mutations)." (PMID 27437068, 2016). "Mutations in FLT3 and KIT have been shown to play a role in the development of malignancies such as acute myeloid leukemia (AML) and advanced systemic mastocytosis (ASM)." (PMID 24085261, 2013). "Clinically, mutations in the KIT proto-oncogene have been frequently reported in various cancers, including gastrointestinal stromal tumors, mast cell tumors, mastocytosis, and acute myeloid leukemia (AML)." (PMID 41557655, 2026). "Recently, a CD56+CD16-CD127+NKp80+CD94+c-KIT- ILC1-like population has been identified in blood of patients with acute myeloid leukemia with a similar profile to various developmental stages of NK cells." (PMID 35833139, 2022). "Midostaurin has a broad inhibition spectrum, with many kinases, beyond KIT, among its targets (for example, being also a Flt3 inhibitor, it is used also in acute myeloid leukemia)." (PMID 35159005, 2022). "A new, continuous cell line overexpressing mutant human kinase KIT(N822K) has been generated using FDC-P1cytokine-dependent murine acute myeloid leukemia cells with a low expressionlevel of the wildtype KIT gene." (PMID 32477598, 2020). "For example, in acute myeloid leukemia, miR-193a can repress c-KIT proto-oncogene expression and function as a tumor suppressor silenced by methylation." (PMID 29016617, 2017). "Among all the studied cells, cells of acute myeloid leukemia expressing the KIT oncogene were the most sensitive to the toxic actions of binase; Kasumi-1 cells undergo apoptosis induced by binase at concentration 0.5 μg/ml." (PMID 28804220, 2017).